IL32 (interleukin 32)
Description:
Cytokine that may play a role in innate and adaptive immune responses. It induces various cytokines such as TNFA/TNF and IL8. It activates typical cytokine signal pathways of NF-kappa-B and p38 MAPK.
Synonyms: NK4; TAIF; TAIFb; TAIFd; IL-32alpha; IL-32beta; IL-32delta; IL-32gamma; TAIFa; TAIFc
Tractability: Antibody: UniProt places it where antibodies can reach, with high confidence; UniProt predicts a signal peptide or a membrane-spanning region; its Gene Ontology location is reachable by antibodies, with medium confidence. PROTAC: ubiquitination databases record sites on it; its protein half-life has been measured.
Gene: Protein-coding gene on chromosome 16 (3,064,301 to 3,082,192, forward strand). Ensembl gene ENSG00000008517.
Subcellular location: Secreted
Pathways (Reactome):
Immune System: Other interleukin signaling
Signal Transduction: RAC3 GTPase cycle
Gene Ontology:
Molecular function: protein binding
Biological process: cell adhesion; defense response; immune response
Cellular component: membrane; cytosol; extracellular region
Genetic constraint (gnomAD): Loss-of-function variants: 31 observed, 18.34 expected, observed/expected ratio (o/e) 1.69, 90% interval 1.24 to 1.95. The upper end of that interval is the gene's LOEUF score, 1.95, which puts it in group 6 of 6, group 1 being the genes least tolerant of losing a copy. Missense variants: 234 observed, 190.74 expected, observed/expected ratio (o/e) 1.23, 90% interval 1.1 to 1.37. Synonymous variants: 70 observed, 65.01 expected, observed/expected ratio (o/e) 1.08, 90% interval 0.89 to 1.31.
Homologues: Orthologues: chimpanzee IL32 (91% identical).
Diseases named in the same sentence as IL32 in open-access papers:
IL32 is named in the same sentence as 237 diseases in open-access papers, as found by Europe PMC text mining. Sharing a sentence is not in itself a finding about the gene and the disease. The quoted sentences say what the papers report.
rheumatoid arthritis (51 papers, 2006 to 2025). A chronic, systemic autoimmune disorder characterized by inflammation in the synovial membranes and articular surfaces. "IL-32 is similarly associated with chronic inflammatory diseases, including rheumatoid arthritis and chronic obstructive pulmonary disease." (PMID 40826444, 2025). "In people with rheumatoid arthritis the SNP rs4786370 (T/C) CC genotype in the IL32 promoter was associated with a favorable lipoprotein profile but also with higher IL-32 and pro-inflammatory cytokine production by PBMC." (PMID 40977709, 2025). "IL-32 is highly associated as well with disease conditions relating to these cell types, like rheumatoid arthritis, COPD, asthma, atopic dermatitis (AD), and certain cancers." (PMID 35281066, 2022). "IL-32 has since been associated with cancer, viral infection, and inflammatory diseases such as rheumatoid arthritis (RA), ankylosing spondylitis, chronic obstructive pulmonary disease (COPD), and graft-versus-host disease (GVHD)." (PMID 25245533, 2014). "IL-32 has also been implicated in several inflammatory disorders, including rheumatoid arthritis, Crohn's disease, atopic dermatitis, chronic obstructive pulmonary disease, and allergic rhinitis." (PMID 23190696, 2012). "IL-32 appears to play an important role in pathophysiologic states associated with dysregulated inflammatory responses, including rheumatoid arthritis, chronic obstructive pulmonary disease, psoriasis, and inflammatory bowel disease." (PMID 21649914, 2011). "Additionally, the CC genotype of rs4786370 has been shown to be associated with slightly increased IL‐32 expression in patients with rheumatoid arthritis." (PMID 34799941, 2022). "Interestingly, increased HDL has been associated with an IL-32 promoter single nucleotide polymorphism (SNP) in rheumatoid arthritis patients, implying an anti-inflammatory role of IL-32 in CVD." (PMID 34422917, 2021). "Additionally, IL-32 has been linked to other inflammatory diseases, including psoriasis, Crohn disease, and rheumatoid arthritis." (PMID 21649914, 2011). "Numerous studies have reported that IL-32 is associated with cancer growth and development, viral infections, as well as chronic inflammatory diseases such as Crohn’s disease, inflammatory bowel disease, and rheumatoid arthritis, which demonstrated the ability of IL-32 to function as a cytokine." (PMID 37228610, 2023). "Most autoimmune and inflammatory diseases associated with IL-32 are rheumatoid arthritis (RA), inflammatory bowel disease (IBD), psoriasis, chronic obstructive pulmonary disease (COPD), and asthma." (PMID 35281066, 2022). "This potential role is further supported by the increased levels of IL-32 in chronic inflammatory diseases linked with CVD such as rheumatoid arthritis (RA), inflammatory bowel disease (IBD) and chronic obstructive pulmonary disease (COPD)." (PMID 33936102, 2021). "This is in line with others, showing that the protective role of IL-32 during the development of atherosclerosis is related to a single promoter single-nucleotide polymorphism (SNP) in IL-32, contributing to modified lipid profiles, especially in rheumatoid arthritis patients." (PMID 34422917, 2021). "In ankylosing spondylitis IL-32γ was elevated in the synovial fluid and in rheumatoid arthritis IL-32 was raised in synovial biopsies, correlating with pro-inflammatory cytokine levels and decreased with anti-TNFα therapy." (PMID 40977709, 2025). "In recent years, IL-32 has emerged as a novel pro-inflammatory cytokine that plays a central role in various inflammatory conditions such as rheumatoid arthritis and inflammatory bowel disease, but also in infections and cancer." (PMID 37727785, 2023). "Previous studies of models of colitis and rheumatoid arthritis have suggested that this alternative splicing of IL-32 plays a role in the self-imposed limitation of uncontrolled inflammation." (PMID 35880892, 2022).
rheumatoid arthritis (continued). "Of note, IL-32 contributes to activation of Janus-activated kinase-1 (JAK1) to promote immune-mediated inflammation of rheumatoid arthritis." (PMID 35545774, 2022). "Like IL-32, IL-34 is also up-regulated in diseased tissues including for inflammatory bowel disease, rheumatoid arthritis, and ischemia/reperfusion injury driven acute kidney injury, however it is down-regulated in gastric cancer." (PMID 36438052, 2022). "IL-32 participates in many diseases, such as rheumatoid arthritis, chronic obstructive pulmonary disease (COPD), and lymphoma." (PMID 36505098, 2022). "IL-32 and IL-34 are key cytokines driving the development of chronic inflammatory conditions such as rheumatoid arthritis, systemic lupus erythematosus, as well as chronic liver diseases." (PMID 36438052, 2022). "Overexpression of IL-32 has been reported in rheumatoid arthritis (RA) and Crohn's disease, as well as, in human symptomatic atherosclerotic plaques, compared to asymptomatic individuals." (PMID 34422917, 2021). "IL-32 has been reported to induce activation of ERK in fibroblast-like synoviocytes in rheumatoid arthritis and human calcified aortic valves." (PMID 31936044, 2020). "Recently, abnormal expression of IL-32 has been linked to various inflammatory or autoimmune diseases, including rheumatoid arthritis (RA), inflammatory bowel disease (IBD), systemic lupus erythematosus (SLE), allergic rhinitis, Behcet's disease, psoriasis and psoriatic arthritis." (PMID 31616372, 2019). "In recent decades, abnormalities in the expression and production of IL-32 have been identified in many human disorders such as rheumatoid arthritis, various cancers, pulmonary tuberculosis, atopic dermatitis, leishmaniasis, etc.." (PMID 29538330, 2018). "In a previous study from our group, IL-32 was found to be highly expressed in synovial tissues from patients with moderate and severe rheumatoid arthritis and it was strongly correlated with the severity of joint inflammation." (PMID 28134327, 2017). "IL-32 is a multifunctional secreted protein that plays important roles in antimicrobial pathways, cancer, and autoimmune diseases, including rheumatoid arthritis (RA), myasthenia gravis, and giant cell arteritis." (PMID 27069296, 2016). "Given that IL32 has an established role in promoting inflammatory arthritis in mouse models and adult rheumatoid arthritis, further work to understand the role of IL32 in JIA is well justified." (PMID 26057774, 2015). "Several studies have shown that IL-32, an important proinflammatory cytokine in rheumatoid arthritis, enhanced IL-6 and IL-8 production in fibroblast-like synoviocytes." (PMID 25386048, 2014). "Interleukin (IL)-32 and IL-17 play critical roles in pro-inflammatory responses and are highly expressed in the synovium of patients with rheumatoid arthritis (RA)." (PMID 23148681, 2012). "For instance, IL-32, while generally considered anti-osteoclastogenic here, has also been reported to exert pro-inflammatory effects under certain conditions, contributing to disease progression in rheumatoid arthritis and other inflammatory states." (PMID 40711169, 2025). "Therefore, in this study, we primarily investigated the role of ENO1 in IL-32 synthesis in Con A-mediated PBMCs and RA PBMCs derived from patients with rheumatoid arthritis." (PMID 38675491, 2024). "In addition, the involvement of IL-32 in the development of other autoimmune diseases, such as rheumatoid arthritis, has already been described." (PMID 35122482, 2022). "IL-32 participates in inflammatory diseases such as rheumatoid arthritis." (PMID 34712431, 2021). "The proinflammatory role of IL-32 has been well reported in several disorders including rheumatoid arthritis, cancers, pulmonary tuberculosis, etc., and also in many skin disorders such as atopic dermatitis, hidradenitis suppurativa, leishmaniasis, and systematic lupus erythematosus." (PMID 29538330, 2018).
rheumatoid arthritis (continued). "Interleukin (IL)-32 is an inflammatory cytokine induced by Mycobacterium tuberculosis and Mycobacterium bovis in a variety of cell types and discovered in the synovial of patients with rheumatoid arthritis (RA)." (PMID 23190696, 2012). "IL-32 synthesis by FLSs is tightly regulated by innate immunity in rheumatoid arthritis." (PMID 20615213, 2010). "Moreover, it has been reported recently that in a cohort of patient suffering with rheumatoid arthritis, IL-32 was significantly increased in the synovial tissue and that its levels were strongly correlated with the severity of the disease." (PMID 19137064, 2009). "IL-32 has the typical properties of a pro-inflammatory mediator and although its role in rheumatoid arthritis has been recently reported its effect on the osteoclastogenesis process remains unclear." (PMID 19137064, 2009). "Moreover, IL-32 mRNA expression was prominent in the synovial tissues of rheumatoid arthritis patients, especially in synovial-infiltrated lymphocytes by in situ hybridization." (PMID 17078892, 2006). "IL-32 induces the production of pro-inflammatory cytokines such as tumor necrosis factor (TNF)-α, IL-1β, IL-6, and IL-8, and IL-32 expression is highly increased in rheumatoid arthritis (RA) patients." (PMID 38675491, 2024). "Unsurprisingly, an increasing number of studies explored the involvement of IL-32 in autoimmune-inflammatory rheumatic diseases (AIRD), such as rheumatoid arthritis (RA), ankylosing spondylitis (AS), psoriatic arthritis (PsA), as well as SLE." (PMID 39835128, 2024). "For instance, IL-32 leads to activated JAK1, which promotes immune-mediated inflammation of rheumatoid arthritis." (PMID 35545774, 2022). "IL-32 has been implicated in inflammatory bowel disease (IBD) and rheumatoid arthritis (RA) where it is thought to orchestrate a panoply of other cytokines; indeed, in RA, IL-32 participates in the interplay with IL-17 in disease pathogenesis by amplifying inflammation in the synovium." (PMID 34262563, 2021). "It has been also reported that the increase of IL-32 expression correlates with clinical and histological markers of diseases such as rheumatoid arthritis (RA), suggesting the reduction of IL-32 activity may provide benefit to patients with RA." (PMID 26564962, 2015). "The IL-32-induced TNF production plays a role in inflammatory diseases such as inflammatory bowel disease and rheumatoid arthritis." (PMID 24884781, 2014). "Interleukin 32 (natural killer protein-4) might be the most interesting gene from this list, as this cytokine has been reported to play a central role in acute flares of inflammatory bowel disease, as well as other autoimmune diseases such as Rheumatoid arthritis." (PMID 23521917, 2013). "Owing to such proinflammatory properties, IL-32 has been considered to play a key role in the development of various inflammatory diseases, including rheumatoid arthritis (RA), inflammatory bowel disease, mycobacterial or viral infection, chronic obstetric pulmonary disease, and pancreatic tumor." (PMID 22613074, 2012). "IL-32 is involved in the pathogenesis of a number of chronic inflammatory diseases and allergic diseases including but not limited to rheumatoid arthritis (RA), chronic obstructive pulmonary disease (COPD), COPD exacerbation, inflammatory bowel disease (IBD), chronic rhinosinusitis and asthma." (PMID 29940981, 2018). "IL32 levels showed positive correlations with tumor necrosis factor alpha, ESR, C-reactive protein, replication factor, and Disease Activity Score 28 genes in rheumatoid arthritis." (PMID 25100201, 2014). "Elevated IL-32 concentrations in synovial fluids and synovial tissues were demonstrated in rheumatoid arthritis but not in osteoarthritis patients." (PMID 24705103, 2013).
rheumatoid arthritis (continued). "Interleukin-32 (IL-32), first identified as natural killer cell transcript 4 (NK4), is a (generally) proinflammatory cytokine that has gained attention for its potential role in various inflammatory and autoimmune diseases, such as rheumatoid arthritis and inflammatory bowel disease." (PMID 40977709, 2025). "IL-32 is known to play an important role in inflammatory diseases such as inflammatory bowel diseases (IBD) and rheumatoid arthritis (RA)." (PMID 38675491, 2024). "In addition, IL-32 is substantially co-localized with pro-inflammatory cytokines (TNF, IL-1β, IL-6) in inflamed tissues in the context of inflammatory bowel disease, in synovial tissues from rheumatoid arthritis or serum from psoriasis patients." (PMID 36438052, 2022). "IL32 is a cytokine induced by TNF-α and may play a critical role in rheumatoid arthritis." (PMID 21423713, 2011). "Interleukin (IL)-32 is a recently described cytokine produced by T lymphocytes, natural killer cells, epithelial cells, mast cells, keratinocytes, eosinophils, and blood monocytes and was discovered in the synovial of patients with rheumatoid arthritis but not osteoarthritis." (PMID 23190696, 2012).
breast carcinoma (36 papers, 2013 to 2025). "The overexpression of IL-32 increases the tumor size and lymph node metastasis in breast cancer, and IL-32 expression is also associated with tumor metastasis and cancer cell migration in gastric and lung cancers." (PMID 34682815, 2021). "IL-32 expression is associated with increased invasion and migration in breast tumors and exerts modulatory effects on the growth and survival of breast cancer cells." (PMID 30648081, 2018). "IL32 is a cytokine and cytokines have also been implicated in breast cancer pathogenesis." (PMID 25100201, 2014). "We then performed a distribution analysis of the assigned IL32 isoform-specific sequences in the single-cell RNA sequencing (scRNASeq) data from breast cancer patients." (PMID 39211051, 2024). "IL-32, also known as NK4, secreted by CAFs stimulates the invasion and metastatic potential of breast cancer cells via activation of integrin β3-p38 MAPK." (PMID 37496657, 2023). "In a previous study, IL32 secreted by CAF promoted breast cancer cell invasion and metastasis through integrin β3-p38 MAPK signaling." (PMID 37234985, 2023). "The specific binding of CAF-derived IL-32 to ITGB3 activates the p38 MAPK cascade signaling pathway in breast cancer cells." (PMID 37217855, 2023). "They found that IL-32, interacting with β3 integrin, plays a significant role in the invasiveness of breast cancer." (PMID 38258051, 2023). "Studies have also demonstrated that interactions between CAFs and breast cancer cells, which are mediated by IL-32 and integrin β3 (ITGB3), play a crucial role in CAF-induced cancer metastasis." (PMID 37217855, 2023). "It is also observed in breast cancer cells that IL-32 secreted by CAFs activated p38 MAPK signaling to promote EMT." (PMID 38186580, 2023). "It has demonstrated that IL-32-STAT signaling pathway was involved in the regulation of tumor progression in breast cancer." (PMID 35428295, 2022). "IL-32 has also been involved in various cancers, including renal cancer, esophageal cancer, lung cancer, gastric cancer, breast cancer, pancreatic cancer, lymphoma, osteosarcoma, breast cancer, colon cancer, and thyroid carcinoma." (PMID 35069212, 2021). "In contrast to breast cancer and small cell lung cancer, we have identified that IL-32 is derived from Treg cells in bladder cancer tissues." (PMID 35069212, 2021). "The fact that IL32 expression is involved in various cancer malignancies, including breast cancer (BRCA) and colon adenocarcinoma (COAD), is well known." (PMID 34682815, 2021). "Regarding proliferation, our findings oppose a role attributed to IL-32γ and β in the colon but are in agreement with the pro-proliferative activity of IL-32 in breast cancer." (PMID 33020452, 2020). "Increasing evidence demonstrates that IL32 has a positive effect on invasion and migration in breast cancer cells and human gastric cancer cells." (PMID 31685803, 2019). "IL32 gene however appears to demonstrate differential expression when compared across different types of breast cancers." (PMID 28966727, 2017). "The present study aimed to examine the potential regulatory effects of IL-32 on breast cancer cells in nude mice." (PMID 25435980, 2015). "In conclusion, the results of the current study suggest that IL-32 exerts modulatory effects on the growth and survival of breast cancer cells." (PMID 25435980, 2015). "The present study aimed to examine the potential effects of IL-32 on the development and progression of breast cancer." (PMID 25435980, 2015). "It is premature to suggest such a role for IL32, but recent studies suggest that particular immune cells and genes are clinically useful as prognostic or predictive indicators for breast cancers." (PMID 25100201, 2014). "We report IL32 levels in breast cancer cells and clinical samples in which the receptor status and diagnosis has been previously determined." (PMID 25100201, 2014).